C5AR1 (complement C5a receptor 1)
Diseases named in the same sentence as C5AR1 in open-access papers (continued):
Sharing a sentence is not in itself a finding about the gene and the disease.
ovarian cancer (20 papers, 2019 to 2025). A primary or metastatic malignant neoplasm involving the ovary. "Complement effectors, C1q or anaphylatoxins C3a and C5a, and their receptors, C3aR and C5aR1, play a prominent role in ovarian cancer progression." (PMID 39135097, 2024). "Some studies have used the syngeneic intraperitoneal injection of ID-8-MOSEC, a mouse epithelial ovarian cancer cell line originating in C57BL/6 mice, to evaluate the roles of C3, C5, and C5aR1 in ovarian cancer development and progression." (PMID 34359708, 2021). "Recent insights suggest an important role of complement effectors, such as C1q or anaphylatoxins C3a and C5a, and their receptors C3aR and C5aR1 in ovarian cancer progression." (PMID 34359708, 2021). "RPS19 was reported to be overexpressed in breast and ovarian cancer, and its interaction with C5AR1 could induce the secretion of immunosuppressive cytokines and promote the generation of Treg cells." (PMID 34611125, 2021). "Although this interaction has never been described in the context of glioma, the ribosomal protein S19 (RPS19) is upregulated in breast and ovarian cancers, and its interaction with the C5a receptor 1 (C5AR1), expressed on tumor-infiltrating myeloid cells, has an immunosuppressive effect." (PMID 33155039, 2020). "In ovarian cancer models, genetic deletion or pharmacological blockade of C5aR1 led to reduced endothelial cell activation and impaired neovascularization, while activation of C3aR and C5aR1 on immune and stromal cells stimulated angiogenesis through VEGF-dependent pathways." (PMID 41488658, 2025). "In the context of ovarian cancer, Zhang demonstrated that C5aR1 blockade reshapes the immunosuppressive tumor microenvironment in high-grade serous ovarian cancer, suggesting that targeting complement signaling could enhance the effectiveness of immune checkpoint blockade therapy." (PMID 38178252, 2024). "Ovarian cancer cells overexpress ribosomal protein S19 (RPS19), which leads to tumor growth through its interaction with C5aR1 in MDSCs." (PMID 34359708, 2021).
asthma (19 papers, 2012 to 2025). "Interestingly, the changes in expression of lectin galactoside-binding soluble 9 (LGALS9), chemokine (C-X3-C motif) ligand 1 (CX3CL1) and complement component 5a receptor 1 (C5AR1) have been previously reported to be associated with asthma." (PMID 25706956, 2015). "Increased C3aR and C5aR1/R2 expression has been confirmed during asthma in in-vivo asthma models, generated via treatment of mice with inhaled allergens, such as ovalbumin (OVA) and LPS." (PMID 38178176, 2024). "In contrast, blockade of the C5aR1 signaling during the effector phase decreased the asthmatic phenotype, demonstrating that C5a is pro-allergic in established asthma." (PMID 28231307, 2017). "Given the role of C5a, the strongest anaphylatoxin, and of C5aR1 as critical regulators of asthma and oral antigen-induced anaphylaxis, we then hypothesized the involvement of C5aR1 also in another paclitaxel-induced side effect, HSRs and anaphylaxis." (PMID 35614037, 2022). "Interestingly, genes previously associated with asthma, such as CCL5 (RANTES), CXCL10 (IP10), LGALS9, CX3CL1, C5AR1, and CDHR3 fall into these three different groups." (PMID 25706956, 2015).
gastric cancer (17 papers, 2016 to 2025). A primary or metastatic malignant neoplasm involving the stomach. "Therefore, we propose that complement C5aR1 is associated with both the development of gastric cancer and iron deposition." (PMID 39850877, 2024). "Our previous research indicated that complement C5a is frequently activated in gastric cancer tissues and promotes the progression of gastric cancer by binding to C5a receptors (C5aR1) expressed on gastric cancer cells." (PMID 39850877, 2024). "Next, we confirmed the high expression of C5aR1 in gastric cancer tissue and its correlation with patient prognosis." (PMID 39850877, 2024). "Survival analysis using data from the KMPLOT website indicated a correlation between C5aR1 expression levels and patient prognosis in gastric cancer, with patients exhibiting lower C5aR1 expression experiencing improved overall survival rates." (PMID 39850877, 2024). "Given that M2 macrophages are known to facilitate tumor iron transport, we conclude that C5a-C5aR1 accelerates iron transport in gastric cancer by promoting M2 polarization of macrophages." (PMID 39850877, 2024). "Subsequently, to confirm the relationship between complement C5a-C5aR1 and the development of gastric cancer and iron deposition, we stimulated human macrophage THP-1 with or without C5aR antagonist using recombinant C5a protein." (PMID 39850877, 2024). "Correlation of C3, CR4, and C5aR1 expression and clinical prognosis in gastric cancer with different clinicopathological factors via Kaplan-Meier plotter." (PMID 33614473, 2020). "C5aR1 signaling promotes motility and invasiveness through the activation of RhoA, and leads to enhanced invasion and vascular invasion in gastric cancer cells." (PMID 31001273, 2019). "Furthermore, these findings are consistent with previous research on the role of C5aR1 in promoting the invasion of gastric cancer cells." (PMID 40056975, 2025). "We explored alterations in C5aR1 expression within gastric cancer (GC)." (PMID 39850877, 2024). "Furthermore, in animal models of lung cancer, gastric cancer, or ovarian cancer, anti-C5a treatment or C5aR1 knockdown, silencing or inhibition decreased proliferation, tumour vascularisation, tumour growth, and metastatic burden." (PMID 33606748, 2021). "Honghong Shen also demonstrated that C5aR1 shaped a non-inflammatory tumor microenvironment and mediates immune evasion in gastric cancer." (PMID 39850877, 2024).
Obesity (16 papers, 2013 to 2025). Accumulation of substantial excess body fat. "The complement and coagulation cascade pathways promote inflammation in adipocytes and obesity-associated co-morbidities, in which C5aR1 is a significant prevalent receptor." (PMID 32684073, 2020). "In addition, IGFBP-2, the mostly highly accumulated from C5aR1−/− adipocytes, is associated with reduced susceptibility to obesity and improved insulin sensitivity, further supporting the injurious role of C5aR1 in adipose inflammation and dysfunction." (PMID 30294325, 2018). "Other work has suggested possible compensatory effects from its sister anaphylatoxin receptor C5aR1, with increased cold-induced adipocyte browning and attenuated diet-induced obesity seen in C3aR1/C5aR1 double KO mice." (PMID 39773465, 2025). "Moreover, the inhibition of C5AR1 is proposed as a therapeutic strategy in cardiovascular diseases; nonetheless, the role of C5AR1 in obesity and inflammation is still not fully understood." (PMID 30509175, 2018).
atherosclerosis (14 papers, 2014 to 2025). A disease characterized by the build-up of fatty material and calcium deposition in the arterial wall resulting in partial or complete occlusion of the arterial lumen. "In the cardiovascular system, C5 has been reported to exacerbate atherosclerosis, and C5aR1 antagonism was linked to the amelioration of atherosclerotic disease in murine models." (PMID 41189475, 2025). "GPR158 is highly expressed in the brain and associates to nervous system-related tumors and cardiac fibrosis, whereas C5AR1 associates to atherosclerosis, coronary artery disease (CAD), and CD." (PMID 39187864, 2024). "Also in atherosclerosis, the role of C5aR2 is less clear, in contrast to the clear-cut pathogenic role of C5aR1." (PMID 28706957, 2017). "The pro-inflammatory roles of C5aR2 and its partner C5aR1—the classical receptor for C5a have been shown in several experimental disease models using C5ar1-/- and C5ar2-/- mice, for example, atherosclerosis, renal ischemic reperfusion injury, and sepsis." (PMID 39021433, 2024). "C5AR1, a receptor for the complement component C5a—a potent pro-inflammatory mediator—can enhance the adhesion and migration of inflammatory cells in atherosclerosis, increasing inflammatory responses and plaque instability." (PMID 39700090, 2024). "This proatherogenic role of C5aR2 and its collaboration with C5aR1 were confirmed in vivo mouse models of wire-induced endothelial injury and high-fat diet-induced atherosclerosis." (PMID 28706957, 2017). "Therefore, here we studied the role of FcγRIII in neointima formation after mechanical arterial injury in comparison with its role in chronic high-fat diet-induced atherosclerosis, and determined the effects of the cooperative role of FcγRIII/C5aR1 in atherosclerotic vascular inflammation." (PMID 32625118, 2020).
melanoma (14 papers, 2015 to 2025). A malignant, usually aggressive tumor composed of atypical, neoplastic melanocytes. "We found that C3, C3AR1, and C5AR1 are associated with T-cell dysfunction phenotypes in two (GSE12417_GPL570 and TCGA melanoma) of the five datasets enumerated." (PMID 34439277, 2021). "Differential methylation of C5AR1 is associated with T-cell dysfunction phenotypes in brain, breast, cholangio, endometrial, esophageal, kidney, lung, melanoma, and uveal cancer." (PMID 34439277, 2021). "As expected, we found that high expression of C3, C5, C3AR1, and C5AR1 is associated with worse ICB outcomes in melanoma and bladder cancer." (PMID 34439277, 2021). "In consistent with a previous report in a melanoma bearing murine model 42, we showed that in contrast to C5aR1, C5aR2 deficiency accelerated tumor development, suggesting an anti-inflammatory role of C5aR2 in AOM/DSS-induced CRC tumorigenesis." (PMID 32754267, 2020). "In conclusion, the complement components C3, C5, C3AR1, and C5AR1 demonstrated a context-dependent association with tumor immune evasion, prognosis, and therapy response with high implicative value in melanoma, colorectal, brain, breast, stomach, and renal cancer." (PMID 34439277, 2021). "In a melanoma mouse model, the activation of autocrine C5aR1 on tumor-infiltrating CD8+ T cells altered their antitumor activity and promoted cancer progression." (PMID 41373839, 2025). "Another complement blocking agent is PMX53 that can block the C5aR1 and allow a reduction of the tumor size, in lung and melanoma mouse models." (PMID 33113844, 2020). "Furthermore, C5aR1 signaling induces the secretion of chemokine C-C motif ligand 2 (CCL2) by melanoma cells." (PMID 40370471, 2025). "In C5aR1-/- mice with melanoma, the tumor volume, MDSCs, and regulatory T cells were decreased." (PMID 36290882, 2022).
hepatocellular carcinoma (13 papers, 2018 to 2025). A malignant tumor that arises from hepatocytes. "β-Sitosterol inhibits hepatocellular carcinoma progression by targeting the complement C5a receptor 1/AFP axis to activate autophagy and suppress cell proliferation and migration." (PMID 39315094, 2024). "In the first study, increased expression of C5aR1 was found in hepatocellular carcinoma and hepatocellular carcinoma-derived cell lines and positively correlated with stage and invasion of liver capsule by tumor cells." (PMID 30061895, 2018). "In addition, C5α can also promote the malignant development of HBc-positive hepatocellular carcinoma through C5AR1." (PMID 37744272, 2023). "C5aR1 was found to promote metastasis by inducing EMT in hepatocellular carcinoma." (PMID 36192575, 2023). "C5a/C5aR1 axis mediates the upregulation of transcription factor Snail and a concomitant decrease in E-cadherin and claudin-1 gene expression levels with increased invasiveness in hepatocellular carcinoma." (PMID 31001273, 2019). "In addition, C5aR1 could promote the expression and secretion of interleukin-6 (IL-6) in hepatoma cells." (PMID 36294966, 2022). "Therefore, C5AR1 has a major role in the growth and migration of hepatoma cells mediated by HBc." (PMID 34948447, 2021). "Based on the C5AR1, HBc facilitates the activation of intracellular signal pathways (such as c-Jun N-terminal kinase (JNK) and ERK pathways) as well as the expression and secretion of interleukin (IL)-6 in hepatoma cells." (PMID 34948447, 2021).
cognitive deficits (12 papers, 2009 to 2026). "The use of PMX205 to inhibit C5a-C5aR1 activity reduces presynaptic over-pruning and rescues cognitive impairment caused by synaptic loss." (PMID 40313098, 2026). "In experimental malaria models, in utero exposure-induced cognitive deficits in the offspring are mediated by C5aR1 signaling, suggesting detrimental consequences of excessive C5aR1 signaling activity on CNS development." (PMID 33613523, 2020). "Importantly, pharmacological and genetic manipulations have provided evidence that C5aR1 signaling is necessary for synaptic dysfunction and cognitive impairments in AD genetic mouse models." (PMID 38053635, 2023). "It is known that C5a‐C5aR1 interaction on microglial cells produces a more inflammatory environment and suppresses clearance pathways both of which could contribute to neuronal damage and cognitive impairment." (PMID 38278523, 2024).
periodontitis (12 papers, 2015 to 2025). An acute or chronic inflammatory process that affects the tissues that surround and support the teeth. "Constitutive complement activation is strongly associated with periodontitis because C3-deficient mice as well as C5aR1 antagonist treated mice are protected against periodontitis." (PMID 31749804, 2019). "In accordance with this, it was shown that C5aR1-knockout mice were protected against osteoarthritis and that bone loss in bacteria-induced periodontitis was associated with an increased C5aR1 activity in osteoblasts." (PMID 28614388, 2017). "However, the C5a/C5aR1 axis could play a crucial role in inflammatory bone loss, because C5aR1-deficient mice were protected against inflammatory arthritis and bone loss in periodontitis was found to be associated with increased C5aR1 activity." (PMID 36246887, 2022). "There is evidence that the C5a/C5aR1 axis is critically involved both in physiological bone turnover and in inflammatory conditions affecting bone, including osteoarthritis, periodontitis, and bone fractures." (PMID 30247799, 2018). "Venn diagrams revealed that there were eight shared genes (FAM46C, SLC7A7, LY96, CFI, DDIT4L, CD14, C5AR1, and IGJ) that overlapped between periodontitis and MS which were screened by WGCNA and DEGs." (PMID 38218802, 2024). "In periodontitis, MANSC1 was negatively correlated and the other four hub crosstalk genes (FMNL1, PLAUR, RNASE6, and TCIRG1) were positively correlated with five hub IRRGs, namely, AQP9, C5AR1, CD14, CSF3R, and PLAUR." (PMID 36545026, 2022).
colon carcinoma (11 papers, 2019 to 2025). "Colon tumors (or counterpart tissues in C5- or C5ar1-deficient mice), spleen and blood samples were collected from mice for profiling immunocytes by flow cytometry or IHC assay." (PMID 32754267, 2020). "Expression of C5AR1 on TAMs conferred M2 polarization in colon cancer and enhanced liver metastatic lesions affirming a central role for C5AR1 in metastatic spread; importantly, genetic loss of C5ar1 severely impaired the metastatic ability of colon cancer cells." (PMID 33718121, 2020). "Ding and colleagues reported that C5aR1 antagonist reduced the abundance of MDSCs in colon tumours, whereas increasing CD8+ T‐cell infiltrates, thereby significantly inhibiting tumour development." (PMID 39422697, 2024). "The CXCL family has long been reported as prognostic biomarkers in colon cancer, being involved with inflammatory processes, including genes such as IL-6, C5AR1, and C3 in the IL-6 module." (PMID 31469863, 2019). "In addition, we recently reported a tumorigenic role for intracellular C5a/C5aR1 in colon cancer cells." (PMID 37291119, 2023). "Moreover, in vitro studies demonstrate that anaphylatoxin C5a enhances human colon cancer cell motility and invasiveness via aberrantly expressed C5aR1 on these tumor cells." (PMID 32754267, 2020).
viral infection (11 papers, 2014 to 2025). "The C5aR1 signaling has been implicated in the pathophysiology of several inflammatory diseases including virus-infection-induced diseases that cause lung pathology." (PMID 37104043, 2023). "The C5a/C5aR1 axis was also shown to be a key player in endothelial thromboresistance loss in several pathological conditions, from genetic rare diseases to viral infections." (PMID 36899927, 2023). "Taken together, our findings highlight that the p38 MAPK signaling pathway is important for C5aR1-mediated proinflammatory cytokine production during viral infection." (PMID 39679722, 2025). "The levels of IL-6 and KC were significantly higher in WT than in C5ar1−/− mice infected with IAV alone on Day 8 post viral infection." (PMID 24740152, 2014).
amyotrophic lateral sclerosis (10 papers, 2017 to 2025). Amyotrophic lateral sclerosis (ALS) is a neurodegenerative disease characterized by progressive muscular paralysis reflecting degeneration of motor neurons in the primary motor cortex, corticospinal tracts, brainstem and spinal cord. "We first tested PMX205, a selective C5aR1 antagonist extensively used preclinically and currently undergoing clinical testing for amyotrophic lateral sclerosis (ALS)." (PMID 40695778, 2025). "In a rodent model of amyotrophic lateral sclerosis, both the expression levels of C5aR1 and the number of C5aR1-expressing astrocytes increase in the spinal cord with disease progression." (PMID 34359981, 2021). "For example, studies from in vitro and mouse models of amyotrophic lateral sclerosis (ALS) have also identified the role for C5a/C5aR1 in driving pathology." (PMID 38053635, 2023). "The C5aR1 specific antagonists PMX53 and/or PMX205 have been shown to reduce disease activity in several animal models, including models of central nervous system disease such as brain trauma, amyotrophic lateral sclerosis and Huntington-like neurodegeneration." (PMID 28078911, 2017).
autoimmune disease (10 papers, 2012 to 2025). A disorder resulting from loss of function or tissue destruction of an organ or multiple organs, arising from humoral or cellular immune responses of the individual to their own tissue constituents. "With regards to other autoimmune disease models, C5aR1 has been successfully targeted in patients with AAV, and it has also been studied in many other autoimmune disease models." (PMID 40409177, 2025). "In particular, a central role of C5aR1 has been identified in these models supported by findings in other autoimmune disorders such as anti-myeloperoxidase glomerulonephritis, autoimmune uveitis, and psoriasis." (PMID 36466856, 2022). "C5aR1 exerts a proinflammatory role in several autoimmune diseases, whereas the role of C5aR2 is still enigmatic, with both immune-activating and immunosuppressive functions in inflammatory disease models such as allergic contact dermatitis and allergic asthma." (PMID 36466856, 2022).